IADEN (IGF2BP1 associated definitive endoderm lncRNA)
Synonyms: HIDEN
Gene: Long non-coding RNA gene on chromosome 8 (131,308,545 to 131,317,889, forward strand). Ensembl gene ENSG00000253507.
Gene Ontology:
Biological process: positive regulation of cell population proliferation
Cellular component: cytosol